WNT5A (Wnt family member 5A)
Diseases named in the same sentence as WNT5A in open-access papers (continued):
Sharing a sentence is not in itself a finding about the gene and the disease.
cancer (continued). "Represent the expression analysis of WNT5A with STAD cancer type in different clinical features between cancers and normal samples via the UACLAN database." (PMID 39176352, 2024). "In the field of cancer biology, the role of Wnt5a exhibits intricate and context-dependent characteristics." (PMID 38532410, 2024). "The percentage of SP was augmented when Wnt5a was overexpressed in nasopharyngeal cancer cells, and high rates of CD44+CD24− cells, immunophenotype associated with CSC in some types of cancer, were detected." (PMID 37804416, 2024). "In turn, Wnt5a was transported via MV and exosomes to cancer cells, activating AP-1/c-Jun and increasing the invasiveness properties of cancer cells." (PMID 37804416, 2024). "It is a comprehensive assessment of the expression of WNT5A in different types of malignancies, aiming to elucidate its function and its impact on the advancement of cancer." (PMID 39176352, 2024). "We used UALCAN to study the correlation between WNT5A expression and clinicopathological factors such as age, gender, race, and cancer stage for LUSC and STAD." (PMID 39176352, 2024). "It was reported that Wnt5a promoted the migration and proliferation of cancer cells by activating the PI3K/AKT signaling." (PMID 38509522, 2024). "K-M plotter was used to analyze the correlation between WNT5A gene expression and the OS (P < 0.05) of 21 cancer types." (PMID 39176352, 2024). "The survival data of patients from various cohorts has been categorized based on the specific cancer type in the WNT5A gene." (PMID 39176352, 2024). "Upregulation of several genes, including IGFBP4, RGS2, and WNT5A, that mediate several functions, including growth, differentiation, proliferation, apoptosis, and angiogenesis, were observed in cancer cells after their treatment with DBMSCs." (PMID 39768220, 2024). "According to one study, the most important genetic alterations in WNT5A across diverse cancers are deletions, followed by amplifications." (PMID 39176352, 2024). "The intricate interplay between the AHR and signalling pathways, such as TGF-β, PI3K/AKT/mTOR, NF-κB, FAK/c-Src, and Wnt5a/b-β-catenin, further complicates its role in cancer development." (PMID 39336758, 2024). "In independent investigations, Wnt5a has demonstrated the ability to enhance metastasis in various cancer cell lines." (PMID 39123414, 2024). "Subsequently, we used the cBioPortal platform to analyze genetic variation in the WNT5A gene in various forms of cancer." (PMID 39176352, 2024). "The findings showed that WNT5A experiences significant genomic changes across various cancer types, such as deletions and amplifications." (PMID 39176352, 2024). "The involvement of Wnt5a in regulation of cancer cell invasion, metastasis, metabolism and inflammation renders it a subject of intense research in oncology." (PMID 38532410, 2024). "The findings of this research contribute valuable knowledge for future studies, namely, in early cancer detection and the detection of genetic modifications in WNT5A within patients." (PMID 39176352, 2024). "Represent the expression analysis of WNT5A with LUSC cancer type in different clinical features between cancers and normal samples via the UACLAN database." (PMID 39176352, 2024). "Wnt5a, an important member from the Wnt family, is critical in regulating cancer cell invasion and metastasis via Wnt5a/β-catenin signaling pathway." (PMID 38355574, 2024). "Our findings provide a foundation for investigating the relationship between WNT5A expression and the proportion of immune cells in different types of cancer, particularly in STAD and LUSC." (PMID 39176352, 2024). "Wnt5a affects cancer cells in a context-dependent manner, predominantly activating β-catenin independent pathways." (PMID 38191909, 2024). "Subsequent in vitro analyses using human recombinant Wnt5a protein revealed that cancer cell proliferation and migration were significantly increased by stimulation with Wnt5a." (PMID 38872420, 2024).
cancer (continued). "The marker molecules of the Wnt signaling pathway, Wnt5a, and Wnt8b are required for progression of cancer." (PMID 36814555, 2023). "The data collectively show that by sponging miR-140-3p, miR-382-5p and miR-579-3p, circZNF800 promotes ALK7, FZD3 and WNT5A expression, possibly contributing to cancer stem cell properties of CRC cells." (PMID 37950151, 2023). "JUN, CXCR4, and WNT5A were the top three interaction DEGs in pathways in cancer; H6PD, FH, and ACO2, which associate with glucose metabolism, were the top three interaction DEGS in metabolic processes." (PMID 37601754, 2023). "One important cancer suppressor function of WNT5A is its ability to impair β-catenin signaling, a fundamental cancer promoter signal in this cancer type." (PMID 37998393, 2023). "Wnt5a, which interacts with RoR2 physically and functionally, has been demonstrated to be related to the growth of many different cancers." (PMID 36923505, 2023). "In fact, WNT5a has been previously reported as highly expressed in CAFs45 and has a role in cancer progression." (PMID 36868311, 2023). "Wnt5a and Wnt8b maintain the viability of cancer cells by accelerating the cell cycle, promoting cell proliferation, promoting cell differentiation and senescence, and preventing apoptosis within cells." (PMID 36814555, 2023). "WNT5a is a para- and autocrine β-catenin-independent ligand that has been shown to inhibit or induce cancer." (PMID 37486552, 2023). "Ma and colleagues checked the impacts of the upregulated growth factors in irCAFs, and WNT5A was identified as the primary contributor to the cancer stemness-promoting effects of irCAFs on cancer cells." (PMID 37079123, 2023). "Herein, we showed that PRMT2 facilitates RCC cancer progression by regulating H3R8me2a modification on the WNT5A promoter." (PMID 37173306, 2023). "Consistently, we detected increased mRNA expression of WNT7B (P = 0.0003), as well as WNT10A (P = 0.0023) and WNT5A (P = 0.088), in most cancer samples." (PMID 35850748, 2022). "WNT5A has emerged as an important molecule involved in cancer progression, and recent studies have demonstrated that WNT5A regulates cancer cell invasion, metastasis, metabolism, and inflammation." (PMID 35687691, 2022). "We found that Wnt5a was highly expressed in tumors relative to the para cancer, and the sequencing results of the resistance strain also showed higher expression of Wnt5a." (PMID 35517407, 2022). "Focusing on the roles of CS in regulating cancer hallmark capabilities, we show here the involvement of ROR1, known as a receptor for WNT5A, in CS-E-mediated upregulation of invasion activity in MDA-MB-231 cells." (PMID 35712490, 2022). "Studies have shown that Wnt5a signaling is emerging as an important event in malignancies, including cancer cell proliferation, invasion, metastasis, metabolism, inflammation, and chemo-resistance." (PMID 35210425, 2022). "Wnt-5a overexpression increases the invasiveness and metastatic potential of cancer cells and is closely correlated with cancer progression." (PMID 35453754, 2022). "In the current study, it also became evident that, at the supramolecular level changes in collagen in cancer-invaded ECM, there was an association, direct or indirect, with WNT1, WNT3A, and WNT5A signaling." (PMID 36452484, 2022). "The phenotype of PS female primitive cells with active GSK3β and Wnt5a-dependent proliferative capacities is reminiscent of cancer stem cells." (PMID 36283083, 2022). "The genes observed in this network (CEACAM1, IGF1, MET, MMP1, MMP3 and WNT5A) were upregulated in cSII/III and are known to be linked to invasive properties in several other cancer types." (PMID 35022523, 2022).
cancer (continued). "Up-regulated TrpC5 leads to a strong increase in intracellular calcium concentration [Ca], increased Wnt5a expression and nuclear translocation of β-catenin, leading to reduced cancer differentiation and increased cancer cell stemness." (PMID 35836256, 2022). "Upregulation of several of these genes, for instance, PTPRZ1, WNT5A, S100A4, or ANXA1/2, has been linked to cancer invasion and aggressiveness in some solid tumors, including GBM25–30." (PMID 34112916, 2021). "The highly motile and invasive phenotype of the cancer cells has been mainly attributed to the high expression of WNT5A/B and receptor tyrosine kinase-like orphan receptors 1 and 2 (ROR1/2)." (PMID 34911552, 2021). "The ‘Gene_Corr’ function (in the ‘Cancer Exploration’ section) was used to compare WNT5A (‘Interested Gene’) and YAP1 (‘Gene Expression’)." (PMID 33643710, 2021). "Similar to the case of TGFβ, also in reference to WNT5A, it was indicated that the expression profile is specific to the tissue and can be dependent on the type of cancer." (PMID 33917330, 2021). "In the present study, we have analyzed the prognostic role of genes involved in Wnt5A-ROR signaling in GC using web-based bioinformatics on publicly available ‘The Cancer Genome Atlas (TCGA) datasets." (PMID 34319035, 2021). "Wnt5a is known to be overexpressed in many cancers, but the molecular mechanism of its overexpression is poorly understood." (PMID 33603066, 2021). "On the other hand, expression levels of Wnt5a determine its function as a tumor suppressor or oncogene in specific cancer types." (PMID 34603445, 2021). "Aberrant expression of CTNNB1 and WNT5A has been observed to affect cell proliferation and lead to cancer occurrence." (PMID 34249080, 2021). "Collectively, the analysis presented in this article suggests that WNT5A expression is modulated by YAP/TEAD in several cancer types, although likely leading to different cellular outcomes depending on the tissue or cell type." (PMID 33643710, 2021). "Given that both Wnt5a and abnormal YAP/TAZ signaling have been linked to cancer (see ‘Introduction’), this relationship was further explored using cancer gene expression data." (PMID 33643710, 2021). "Box5 is primarily used for cancer applications and it exerts its effect via directly binding to the receptor of Wnt5a, which inhibits the biological activity of Wnt5a signaling." (PMID 33462195, 2021). "It must be noted, however, that other TFs are likely needed to fine-tune the expression of WNT5A, thus explaining the results observed by surveying cancer expression data." (PMID 33643710, 2021). "MiR-26a inhibits the progression of this cancer by suppressing Wnt5a while hsa-miR-1297 downregulates Wnt/AEG1 pathway signaling." (PMID 35201496, 2021). "Consistent with our in silico data, previous studies have also demonstrated the prognostic role of Wnt5a-ROR signaling genes with several types of cancer." (PMID 34319035, 2021). "High-risk and advanced PCas shared the expression of diverse proteins that are reportedly associated with cancer progression, namely TGF-β, Wnt5a/b, Shc1 (phospho-SHCY317), phospho-c-RAF-S338 and phospho-c-MycT58/S62." (PMID 34155195, 2021). "For instance, certain works emphasize on the significance of Wnt5a and Immature Colon Carcinoma Transcript-1 (ICT1) in prognosis prediction." (PMID 34026619, 2021). "Different roles of WNT5A, especially in various cancers, are partially due to the existence of two isoforms of WNT5A, WNT5A-long and WNT5-short." (PMID 32659938, 2020). "Wnt5a enhances the colony formation ability of these Mist1+ cells and, more importantly, cancer progression is impaired when Wnt5a expression is eliminated in the ILCs in a transgenic mouse model that develops diffuse-type GC following E-Cadherin depletion." (PMID 32195251, 2020). "Our results are consistent with the previously reported effect of WNT5A in embryonic development and several cancer types." (PMID 33178184, 2020).
cancer (continued). "In the transwell invasion assay, the invasive ability of cancer cells co-cultured with Wnt5a-induced M2 macrophages was also enhanced, and this enhancement was suppressed by IL-10 neutralizing antibody." (PMID 32228612, 2020). "In pancreatic PANC-1 and colorectal Caco-2 cell lines, Wnt5a carried by EVs displays the ability to enhance cancer progression." (PMID 33080952, 2020). "A previous study reported that STAT3 interacts with FZD2 and plays a critical role in WNT5a/FZD2-mediated cancer cell metastasis." (PMID 32766155, 2020). "While Wnt5a activation has been shown to inhibit the cell growth, migration, and invasiveness of thyroid and CRC cells, increased Wnt5a expression is involved in the aggressiveness of other types of cancers." (PMID 32650388, 2020). "Collectively, these results demonstrate that TAMs enhance the growth and metastasis of CRC, whereas Wnt5a knockdown impairs the cancer-promoting functions of TAMs in vivo." (PMID 32228612, 2020). "Their research focused on the direct effects of Wnt5a on cancer cells, while ours concentrated on the regulatory role of Wnt5a in TAMs." (PMID 32228612, 2020). "WNT5a has been studied broadly in many different cancer cell types, where there is supporting evidence to show that WNT5a promotes EMT36–39." (PMID 32546756, 2020). "Collectively, these data suggest that Wnt5a mediates the cancer-promoting functions and macrophage recruitment of TAMs via CCL2." (PMID 32140070, 2020). "As for Wnt5a, an activator of Wnt/β-catenin pathway, played a critical role in the progress and development in many malignant tumors." (PMID 33987473, 2020). "Mechanistically, the cancer-promoting roles of Wnt5a in TAMs depended on CaMKII-ERK pathway-mediated CCL2 secretion." (PMID 32140070, 2020). "The migration of cancer cells co-cultured with Wnt5a-induced M2 macrophages was significantly enhanced, which was reversed by IL-10 neutralizing antibody." (PMID 32228612, 2020). "Slow cycling cancer cells are enriched by anti-cancer drugs and confer resistance by activating various signaling pathways, including the WNT5A and EGFR pathways." (PMID 32626712, 2020). "Further experiments revealed that the cancer-promoting functions of Wnt5a in TAMs were dependent on CCL2 secretion." (PMID 32140070, 2020). "Consistent with previous results, the cancer-promoting capacity of TAMs was significantly impaired by Wnt5a knockdown, which was reversed by recombinant CCL2 treatment." (PMID 32140070, 2020). "Wnt5a plays important roles in the processes governing embryonic development and pathological disorders, such as cancer and inflammatory disease, throughout the lifespan of organisms." (PMID 32184820, 2020). "Further investigation demonstrated that Wnt5a was an important inducer of TAMs for their cancer-promoting roles." (PMID 32140070, 2020). "Taken together, these data reveal that M2 macrophages are critical for the cancer-promoting functions of Wnt5a." (PMID 32228612, 2020). "Wnt5a has dual functions of promoting or inhibiting cancer progression, and can play different roles depending on the type of cancer and the background of the receptor." (PMID 32268875, 2020). "This study expands the functional repertoire of Wnt5a that is mainly known as a signalling protein involved in development and cancer." (PMID 31098409, 2019). "Previous studies have demonstrated that Wnt5a has a dual effect on the progression of various types of human cancer, indicating that this pathway is particularly dependent on the cellular context." (PMID 31510045, 2019). "The upregulation of WNT5A, which is linked to the epithelial mesenchymal transition (EMT) process and cancer progression, has also been shown to be induced by NF-κB signaling, as is the rapid transcriptional activation of TNF-α." (PMID 31164956, 2019). "Since inflammation is a critical factor for cancer progression, it is of utmost importance to better understand the role of Wnt5a in this process." (PMID 31510045, 2019).
cancer (continued). "Since Wnt5a signaling has also been involved in inflammatory processes in infectious and inflammatory diseases, we addressed the role of Wnt5a in regulating NF-κB, a pivotal mediator of inflammatory responses, in the context of cancer." (PMID 31510045, 2019). "This included genes like, PIK3R2, PIK3CA, BIRC2 and ZBTB14 with implications in cancer that were over-expressed with FC above ≥10 in OS-DW in comparison to OS-R; while, expression of WNT5A, PIK3CB, ACVR1, MAPK13 and GBX2 were significantly reduced." (PMID 31690262, 2019). "For example, WNT5A promotes cancer through binding its receptor ROR2 and enhancing human osteosarcoma invasiveness." (PMID 31382613, 2019). "A study showed that Wnt receptor, Frizzled 2, and its ligand, Wnt5a/b, were found to be elevated in various cancers that also promote proliferation and cell migration ability." (PMID 31861402, 2019). "Foxy-5 is a hexapeptide mimic of Wnt5a which is synthesized to possess Wnt5a-like properties that can impair cancer cell migration." (PMID 31921137, 2019). "Of note, activation of NF-κB by Wnt5a has been shown in different cellular contexts but has been poorly studied in cancer cells." (PMID 31510045, 2019). "WNT5A has been proved as an important factor for maintaining the cancer stem cell (CSC)-like, tumorigenicity and BLBC phenotype in BLBC cells, was also used in the following study." (PMID 31462314, 2019). "LGK-974 (also known as WNT-974, a Phase I drug for TNBC and other Wnt ligands-dependent cancers) is a Porcupine inhibitor and can inhibit Wnt5a and Wnt5b secretion effectively." (PMID 31462314, 2019). "Numerous studies of how WNT5A signaling affects cancer cell behavior, in vitro, have successfully been performed with rWNT5A." (PMID 30171384, 2018). "WNT5A, linked to the epithelial mesenchymal transition (EMT) process and cancer progression, has been shown to be upregulated by NF-κB signaling." (PMID 29464041, 2018). "Although WNT signaling regulates liver metabolism and can stimulate aerobic glycolysis by mTORC2-AKT signaling during osteoblast differentiation, the direct role of WNT5A in the metabolic reprogramming of cancer is still under-investigated." (PMID 30171384, 2018). "Based on sequence analysis of WNT5A, we identified several peptide sequences predicted to be solvent exposed and thus able to interact with receptor structures exposed on cancer cells." (PMID 30171384, 2018). "Together, these data suggest that proliferation of different types of cancer cell lines depends on Wnt5a/b." (PMID 29453334, 2018). "This analysis showed that WNT5a mRNA expression is significantly upregulated (2.5-fold) in carcinoma compared to normal colon/rectum." (PMID 29453334, 2018). "Since Foxy-5 is a WNT5A mimicking peptide, one can presume that its effects will be more distinct in a cancer cell line with a low endogenous WNT5A expression." (PMID 28886116, 2017). "Recent studies show the involvement of Wnt5a signaling in regulating normal and cancer stem cell self-renewal, cancer cell proliferation, migration, and invasion." (PMID 28491097, 2017). "Many previous studies have demonstrated that Wnt5a is up-regulated in various cancers, including gastric, pancreatic, and prostate cancers." (PMID 29054966, 2017). "For example, Wnt5a was demonstrated to be upregulated in cancers of the lung, breast, stomach, and prostate." (PMID 28859077, 2017). "Adipocytes were shown to promote the proliferation of cancer cells via hepatocyte growth factor (HGF) signaling, and Wnt5a secreted by cancer cells was found to induce lipolysis." (PMID 28407685, 2017). "Wnt5a, a prototypic ligand that activates a β-catenin independent pathway in Wnt signaling, has been demonstrated to exert differential effects on cancer development." (PMID 28289332, 2017). "We demonstrated that the overexpression of the Ror2 receptor as well as the stimulation with Wnt5a and the combination of both perturbations enhance cancer cell invasion." (PMID 28695110, 2017).